TRAV40 (T cell receptor alpha variable 40)
Description:
V region of the variable domain of T cell receptor (TR) alpha chain that participates in the antigen recognition. Alpha-beta T cell receptors are antigen specific receptors which are essential to the immune response and are present on the cell surface of T lymphocytes. Recognize peptide-major histocompatibility (MH) (pMH) complexes that are displayed by antigen presenting cells (APC), a prerequisite for efficient T cell adaptive immunity against pathogens. Binding of alpha-beta TR to pMH complex initiates TR-CD3 clustering on the cell surface and intracellular activation of LCK that phosphorylates the ITAM motifs of CD3G, CD3D, CD3E and CD247 enabling the recruitment of ZAP70. In turn ZAP70 phosphorylates LAT, which recruits numerous signaling molecules to form the LAT signalosome. The LAT signalosome propagates signal branching to three major signaling pathways, the calcium, the mitogen-activated protein kinase (MAPK) kinase and the nuclear factor NF-kappa-B (NF-kB) pathways, leading to the mobilization of transcription factors that are critical for gene expression and essential for T cell growth and differentiation. The T cell repertoire is generated in the thymus, by V-(D)-J rearrangement. This repertoire is then shaped by intrathymic selection events to generate a peripheral T cell pool of self-MH restricted, non-autoaggressive T cells. Post-thymic interaction of alpha-beta TR with the pMH complexes shapes TR structural and functional avidity.
Synonyms: TCRAV31S1; TCRAV40S1
Gene: T-cell receptor variable (V) gene on chromosome 14 (22,314,490 to 22,314,919, forward strand). Ensembl gene ENSG00000211819.
Subcellular location: Cell membrane
Gene Ontology:
Biological process: adaptive immune response
Cellular component: immunoglobulin complex; plasma membrane
Homologues: Orthologues: dog TRAV40 (78% identical). Paralogues in human: TRAV9-2 (52% identical), TRAV9-1 (47% identical), TRAV18 (44% identical), TRAV19 (30% identical), IGKV4-1 (26% identical), IGLV5-52 (26% identical), TRDV1 (26% identical), TRDV3 (26% identical), IGKV1-12 (25% identical), IGKV1D-12 (25% identical), IGKV1D-16 (25% identical), IGKV2D-29 (25% identical), and 81 more.